IL4 (interleukin 4)
Diseases named in the same sentence as IL4 in open-access papers (continued):
Sharing a sentence is not in itself a finding about the gene and the disease.
osteoporosis (continued). "Serum levels of TNF-α, IL-6, and IL-17 were higher and levels of IL-4 and IL-10 were lower in RA patients when compared to those without osteoporosis." (PMID 35955873, 2022). "The relationship between serum levels of IL-4 and osteoporosis has not been well established in men and warrants further investigation." (PMID 33007863, 2020). "Furthermore, it has been observed that Th2 dominance is related with senile osteoporosis, implying that Th2-type cytokines such as IL-10, IL-6, IL-5, and IL-4 levels rose while Th1-type cytokines such as IL-2,IFN-γ and TNF-α reduced in patients suffering from senile osteoporosis." (PMID 38461235, 2024). "Consequently, IL‐4 production by NKT‐like cells, which negatively regulate osteoclast differentiation and proliferation, may be diminished, thereby inducing excessive activation of osteoclasts and subsequently osteoporosis." (PMID 34214248, 2021).
periodontal disease (20 papers, 2014 to 2025). "Conversely, the periodontal diseases are correlated to associated to a Th2 cell-mediated and an overexpression of the IL-4, IL-5, IL-6, and IL-10 mediators." (PMID 35735643, 2022). "Interleukin-4 (IL-4) and interleukin-13 (IL-13) are anti-inflammatory cytokines and several polymorphisms of them have been proved involved in periodontal disease." (PMID 27195298, 2016). "The results of the present study point to the importance of single nucleotide IL-4 gene polymorphisms in periodontal disease." (PMID 25530681, 2014). "Our study suggests that polymorphisms in the IL-4 gene not only affect the production of the IL-4 cytokine but can influence production of several other cytokines, such as IL-10, IFNγ, IL-1β, IL-6, and TNFα, which in turn can affect periodontal disease." (PMID 25530681, 2014). "Analysis of immunological markers reveals statistically significant differences between the two stages of periodontal disease analysed, respectively stage two and stage four for all variables except interleukin 4 (p > 0.05)." (PMID 38920850, 2024). "Previous studies showed that IL-4 acts to improve periodontal disease through its regulatory potential against IL-1 and TNF-α and its ability to induce the death of activated macrophages." (PMID 37026605, 2023). "A number of candidate gene studies showed that IL1A, IL1B, IL4, IL6, IL10, TNFA, FcγR, VDR, TLR2, TLR4, and MMP1 were the main genes associated with periodontal disease." (PMID 36294882, 2022). "The levels of IL-1β, IL-8, and IL-4 were higher in the patients with periodontal disease than in the healthy subjects, although the differences were not statistically significant." (PMID 34199256, 2021). "The biomarkers showing elevated levels in the baseline saliva of patients with periodontal disease were IL-1β, IL-4, IL-6, MMP-8, and TIMP-2, while the control group showed high levels of TNF-a, IL-10, IL-17, and IL-32." (PMID 33383828, 2020). "Biomarkers showing high levels in periodontal disease were salivary IL-1β, IL-4, IL-6, MMP-8, and tissue inhibitor of matrix metalloproteinases (TIMP)-2, and those in the controls were tumor necrosis factor (TNF)-α, IL-10, IL-17, and IL-32." (PMID 33383828, 2020). "IL-4 has been reported to possess a protective role in periodontal disease and could mediate the remission or improvement of periodontal lesions." (PMID 28632755, 2017). "Studies confirm that certain salivary biomarkers, i.e. IFN-γ, IL-1-β1, TNF-α, IL-6, IL-4 and IL-8, may be used for predicting future development of periodontal diseases." (PMID 25976216, 2015). "The decreased monocyte chemotaxis and phagocytosis, the increased production of TNF-alpha, IL-4, IL-10 and IL-1, as well as the increased susceptibility to infections and the delayed healing response, explain the susceptibility of HIV-positive individuals to periodontal disease." (PMID 33916511, 2021). "IL-4 is a cytokine that strongly inhibits macrophage function, including production of PGE2 and cytokines; hence, it was suggested that a local lack of IL-4 may contribute to periodontal disease progression." (PMID 35454140, 2022).
cervical carcinoma (19 papers, 2011 to 2025). A carcinoma arising from either the exocervical squamous epithelium or the endocervical glandular epithelium. "Atopobiaceae (CST IV) were enriched in cLSIL, cHSIL, and cervical carcinoma and positively correlated with IL-1α, IL-4, IL-10, IL-12, IL-36γ, IFN-α2, IFN-γ, and TNF-α in cervicovaginal lavages." (PMID 40362199, 2025). "Within the context of cervical cancer, cytokines IL-4 and IL-10 play pivotal roles in modulating immune responses and tumor expansion." (PMID 39207449, 2024). "Tumor-derived thymic stromal lymphopoietin (TSLP) can activate eosinophil to increase the expression of IL-4, IL-5, IL-10 and IL-13, and promote the proliferation of cervical cancer cells." (PMID 36874093, 2023). "A study of lidocaine administration in women with cervical cancer undergoing radical hysterectomy showed that the ratio of interferon-c to IL-4 was preserved in these women when compared with those who did not receive it." (PMID 35252243, 2022). "Additional studies should also include more solid cancer cell lines in order to see if the synergistic effect of IL-4 plus xanthone 1 in macrophage antitumor activity is similar to what we have observed for prostate and cervical cancer cell lines." (PMID 34207168, 2021). "The immunosuppressive cytokines such as IL-4 and IL-10 have been long investigated in cervical carcinoma, while the IL-1 receptor antagonist has been investigated in relation to epilepsy." (PMID 32899735, 2020). "Results showed that the expression profiles of cytokines detected in the two cervical cancer cell lines were consistent and IL‐2, IL‐4, IL‐6, IL‐8, IFN‐γ, MCP‐1 and TNF‐α were all expressed." (PMID 31943744, 2020). "In this work, we show that B lymphocytes from cervical cancer patients respond to treatment with sCD40L and IL-4 by increasing the CD80+CD86+ population, therefore potentially increasing their ability to activate T cells." (PMID 29975708, 2018). "IL-4 has been shown to be significantly upregulated in tumor infiltrating lymphocytes of cervical carcinoma patient." (PMID 21698244, 2011). "Previously, we reported that IL-10 and TGF-β1 are expressed in cervical lesions; therefore, the development of SIL and cervical cancer is preferentially associated with the expression of immunosuppressive cytokines (IL-10 and TGF-β1) and Th2-type cytokines (IL-4/IL-6)." (PMID 24808638, 2014). "Elevated levels of IL-4, IL-10, and TGF-βI have been observed in the serum of cervical cancer patients, whereas INF-γ concentrations are diminished in this population." (PMID 38881859, 2024). "Fusobacterium has been found to correlate with elevated expression of IL-4 and transforming growth factor (TGF)-β1, suggesting its role in immunosuppression within the microenvironment of invasive cervical cancer (ICC)." (PMID 38881859, 2024). "Fusobacterium predominance is more prevalent in individuals with invasive cervical cancer, where it is found to be related with elevated levels of IL-4 and transforming growth factor (TGF)-β1 mRNA, indicating its immunosuppressive effect in the microenvironment of the invasive cervical cancer." (PMID 36683675, 2022). "IL-4 and IL-10 are expressed in SIL and cervical cancer, but IL-4 is not expressed in normal cervical tissues." (PMID 36726132, 2023).
chronic asthma (19 papers, 2013 to 2025). An asthma that is characterized by the development of persistent airway inflammation and recurrent attacks of breathlessness and wheezing, which vary in severity and frequency. "In contrast, in the chronic asthma model, each of the Th2 cytokine transcripts was modestly reduced in the sPLA2-deficient mice (i.e., reductions of 22% for IL-4, 19% for IL-5, an 49% for IL-13)." (PMID 23451035, 2013). "CycloZ effectively lowered the levels of Th2 cytokines (IL-4, IL-13) and related genes in both acute and chronic asthma models, pointing to its potent anti-inflammatory effects." (PMID 39682780, 2024). "Consistent with the roles of CD146 in the inflammatory response, IL-4, IL-5, IL-1, and IFN-γ levels were significantly reduced in CD146-deficient mice with chronic asthma." (PMID 32793232, 2020). "Furthermore, we noted a significant increase in the serum IL-4 concentration during the induction of chronic asthma reactions in mice." (PMID 40558541, 2025). "Additionally, we observed a strong positive correlation between the IL-4 production and the blood IgE levels following the exposure to the three allergens in the chronic asthma model." (PMID 40558541, 2025). "However, the levels of IL-4, IL-5, and IL-13 substantially decreased in mice with chronic asthma compared with those in mice with acute asthma." (PMID 34671356, 2021). "In addition, our results demonstrated an increase in the levels of the main pro-inflammatory cytokines found in chronic asthma (IL-4, IL-5, and IL-13) and reduced the anti-inflammatory IL-10." (PMID 35185864, 2021). "IL-4 is a major factor in the recruitment and activation of inflammatory cells that may contribute to inflammation and lung remodeling in chronic asthma." (PMID 26758251, 2016). "Notably, miR-378a-3p was the most upregulated miRNA both in IL-4-induced M2 macrophages and the lungs of mice with chronic asthma, which might be involved in M2 polarization of macrophages." (PMID 34589519, 2021). "Both fungal extracts significantly elevated the IL-4, IL-5, IL-13, TNF-α, and TGF-β levels in mice with acute and chronic asthma." (PMID 40558541, 2025). "Inflammatory cytokines in lung homogenate, such as IL-4, IL-5, and IFN-γ, were significantly increased in the chronic asthma model." (PMID 37432745, 2023). "HE staining and ELISA detection results of inflammatory factors (IL-4, IL-5, and IL-13) showed that the inflammatory response was substantially higher in OVA-induced acute asthma (OVA-4 weeks group) than that in chronic asthma (OVA-8 weeks group)." (PMID 34671356, 2021). "In conclusion, our results suggest that in the airways of chronic asthma patients there is an imbalance between the increased population of CD4+IL-17+ cells, CD4+IL-17+IFN-γ+ cells and CD4+IL-4+ cells and the decreased population of CD4+Foxp3+TGF-β+ cells." (PMID 25132806, 2014). "Interestingly, the use of Gal-3 therapy has also shown positive results on murine models simulating chronic asthma, with a significant reduction in key BAL cytokines like IL-5, interleukin-4 (IL-4), and interleukin-10 (IL-10)." (PMID 38785528, 2024). "However, treatment directed at TRPV1 significantly alleviated IL-4, IL-5, and IL-13 level in a chronic asthma murine model, while conversely TRPA1 promoted OVA-induced IL-4 production during acute allergic lung inflammation." (PMID 34099759, 2021). "We found that in BAL fluid of patients with chronic asthma have a decreased population of CD4+Foxp3+TGF-β+ cells and at the same time an increased population of CD4+IL-17+ cells, CD4+IL-17+ IFN-γ+ cells and CD4+IL-4+ cells." (PMID 25132806, 2014). "Curcumin administered intranasally prevented remodeling related to chronic asthma, structural alterations, airway inflammatory cell accumulation, and mucus secretion in the OVA-induced murine model of chronic asthma, along with a decrease in IL-5, IL-4, and IgE levels." (PMID 39263346, 2024).
Crohn disease (19 papers, 2008 to 2025). A gastrointestinal disorder characterized by chronic inflammation involving all layers of the intestinal wall, noncaseating granulomas affecting the intestinal wall and regional lymph nodes, and transmural fibrosis. "Further, IL-4 can have both pro- and anti-inflammatory roles in disease, and in one mouse model of Crohn’s disease-like ileitis, a pathogenic role has been assigned to IL-4." (PMID 40394349, 2025). "Consequently, the development of Lactococcus lactis strains capable of delivering a eukaryotic expression vector encoding the interleukin 4 (IL-4) of Mus musculus would represent a new strategy for the elaboration of a more effective alternative therapy against Crohn’s disease." (PMID 27576902, 2016). "IFN-γ and IL-4 levels were measured in human ileal samples from patients with Crohn’s disease and compared to healthy individuals." (PMID 35805922, 2022). "However, IL-4 may play a significant role in allergic diarrhea, parasitic expulsion, and Crohn’s disease." (PMID 35805922, 2022). "Studies have shown that levels of IL-4 and IL-4 mRNA are reduced in IBD patients, mainly Crohn’s disease patients, indicating a role for this cytokine in the pathophysiological process." (PMID 37189566, 2023). "In patients with Crohn’s disease, the markedly increased amounts of IFN-γ together with markedly decreased levels of IL-4 are observed in T cells isolated from the affected tissues." (PMID 31540496, 2019).
injury (19 papers, 2010 to 2025). Damage inflicted on the body as the direct or indirect result of an external force, with or without disruption of structural continuity. "It is widely reported that IL-4 is closely associated with many brain injury diseases, such as cerebral infarction, transient focal cerebral ischemia, neonatal asphyxia, and hypoxic–ischemic encephalopathy." (PMID 32982939, 2020). "In other models of brain injury, IL-4 has been implicated in the control of the inflammatory response and consequently, in animal recovery." (PMID 30687005, 2018). "VC decreases IL-4, IL-6 and IL-8 level via inhibition of NF-κB signaling pathway in concanavalin A- induced liver injury mice." (PMID 32344708, 2020). "Thus, we treated mice intravenously with 1x106 bone marrow-derived macrophages at steady-state (BMDM φ) or after alternative activation with IL-4 (BMDM A.A) 16h after APAP-induced liver injury." (PMID 35967353, 2022). "A proposed mechanism by which IL-4 promotes cognition is that it exerts its effect through an anti-inflammatory M2-skew of meningeal macrophages, which has been shown to be both beneficial after CNS injury and required for learning." (PMID 24548288, 2014). "When patients with primary MHTN related kidney injury have decreased CD4+CD25+ cells, their lymphocytes would react significantly more strongly to antigens, leading to higher levels of cytokine (IL-2, IL-4, and IL-6) production." (PMID 27278520, 2016). "For example, PGD2 exacerbated dicloxacillin-induced liver injury by enhancing IL-4 production, and anti-TXB2 antibodies protect against acetaminophen-induced liver injury." (PMID 26289793, 2015). "It is known that IL-4 and IL-5 can increase the amount of nerve growth factor, which is secreted by astrocytes after neural trauma, independent of cell growth." (PMID 38334617, 2024). "However, the levels of hepatic TNF-α, IL-1β, IL-4, IL-6, and TGF-β1 were significantly lower in rats with 2-AAF/PH-induced liver injury treated with Pue and RAPA than in untreated rats with liver injury, and IL-10 expression was higher." (PMID 30405406, 2018). "Furthermore, IL-4 treatment failed to enhance oligodendrogenesis and differentiation in oligodendroglial PPARγ conditional knockout mice after ischemic and traumatic brain injury." (PMID 41294810, 2025).
lymphedema (19 papers, 2015 to 2025). Excess fluid collection in tissues, causing swelling. "In fact, we found that inhibiting Th2 differentiation using monoclonal antibodies directed against interleukin-4 (IL-4) or interleukin-13 (IL-13) markedly decreased fibrosis, leading to resolution of pathologies associated with lymphedema and restoration of lymphatic function." (PMID 26039103, 2015). "Neutralizing IFN-γ enhanced inflammatory lymphangiogenesis regardless of VEGF-A and VEGF-C levels, while blocking Th2 cytokines, IL-4 and IL-13, reduced lymphedema and improved lymphatic function." (PMID 40655011, 2025). "Inflammatory mediators such as IL-4, IL-13, TGF-β, and LTB4 are implicated in various pathways that promote lymphedema progression." (PMID 40026487, 2025). "We have previously shown that the inhibition of Th2 differentiation using IL-4- or IL-13-neutralizing antibodies is an effective means of treating lymphedema and improving lymphatic function." (PMID 40426856, 2025). "Th2 cells, a type of helper T cell, mainly secrete cytokines such as IL-4 and IL-13 during the progression of secondary lymphedema." (PMID 40766782, 2025). "Specifically, infiltration of Th2 CD4+ T cells characterized by signature cytokines such as IL-4, IL-5, and IL-13 promotes lymphedema but Treg cells inhibit the development of lymphedema." (PMID 37940849, 2023). "The inflammatory cytokines IFN-γ, IL-4, and IL-17A have been reported to negatively control the formation of lymphatic vessels involved in the progression of lymphedema." (PMID 37250774, 2023). "The inhibition of Th2 differentiation with IL-4- or IL-13-neutralizing antibodies prevents the initiation and progression of lymphedema by inhibiting tissue fibrosis and improving lymphatic function in another mouse tail lymphedema model." (PMID 35886961, 2022). "Based on this pathophysiology, the efficacy of pharmacotherapy (tacrolimus, anti-IL-4/IL-13 antibody, or fingolimod) and cell-based therapy for lymphedema has been demonstrated in animal models and pilot studies." (PMID 35886961, 2022). "Recent studies suggest that Th2 cells play a key role in the pathology of secondary lymphedema by elaborating cytokines such as IL4 and IL13." (PMID 34571811, 2021). "In one study, neutralizing antibodies against interleukin-4 (IL-4) and interleukin-13 (IL-13) were used to treat lymphedema in a mouse model." (PMID 28232732, 2017). "Additionally, a report detailed the efficacy of monthly intravenous QBX258 infusion, a combination of two monoclonal antibodies neutralizing IL-4 and IL-13, in eight patients with breast cancer-related lymphedema." (PMID 35886961, 2022). "Consequently, when these same animals were treated with IL-4 or IL-13 neutralizing antibodies, lymphedema was prevented." (PMID 32268536, 2020). "Additionally, Th2 helper cells are required for the development of lymphedema and Th2 cytokines; IL-4, and IL-13 are anti-lymphangiogenic, adding to the pathophysiology of lymphedema." (PMID 32344864, 2020). "Th2 cells may also be involved in lymphedema pathogenesis as neutralization of two cytokines produced by these cells, IL-4 and IL-13, in a mouse model of secondary lymphedema promoted lymphatic function and restricted fibrosis." (PMID 30761143, 2019). "The number of CD4 cells that expressed Th2 cytokine IL4 and IL5 was increased in patients with lymphedema." (PMID 37886950, 2023). "To understand the correlation between cytokine production by T cells and lymphedema, we compared the expression of IFN-γ, IL-4, and IL-17A on CD4+ and CD8+ T cells in lymphedema, post-LVA, and HCs." (PMID 37250774, 2023). "For instance, CD4+ T cells such as Th1 and Th2 immune paradigms can trigger the release of IL-4, IL-13, and TGF-β1 across tissues and they can control collagen deposition and fibrosis in lymphedema." (PMID 37267206, 2023). "This study aimed to examine the effect of inhibition of Th2 inflammation in lymphedema by using QBX258, a combination of IL4/13 neutralizing antibodies." (PMID 34571811, 2021).